TRGV5 (T cell receptor gamma variable 5)
Description:
V region of the variable domain of T cell receptor (TR) gamma chain that participates in the antigen recognition. Gamma-delta TRs recognize a variety of self and foreign non-peptide antigens frequently expressed at the epithelial boundaries between the host and external environment, including endogenous lipids presented by MH-like protein CD1D and phosphoantigens presented by butyrophilin-like molecule BTN3A1. Upon antigen recognition induces rapid, innate-like immune responses involved in pathogen clearance and tissue repair. Binding of gamma-delta TR complex to antigen triggers phosphorylation of immunoreceptor tyrosine-based activation motifs (ITAMs) in the CD3 chains by the LCK and FYN kinases, allowing the recruitment, phosphorylation, and activation of ZAP70 that facilitates phosphorylation of the scaffolding proteins LCP2 and LAT. This lead to the formation of a supramolecular signalosome that recruits the phospholipase PLCG1, resulting in calcium mobilization and ERK activation, ultimately leading to T cell expansion and differentiation into effector cells. Gamma-delta TRs are produced through somatic rearrangement of a limited repertoire of variable (V), diversity (D), and joining (J) genes. The potential diversity of gamma-delta TRs is conferred by the unique ability to rearrange (D) genes in tandem and to utilize all three reading frames. The combinatorial diversity is considerably increased by the sequence exonuclease trimming and random nucleotide (N) region additions which occur during the V-(D)-J rearrangements.
Synonyms: TCRGV5; V1S5
Gene: T-cell receptor variable (V) gene on chromosome 7 (38,349,355 to 38,350,022, reverse strand). Ensembl gene ENSG00000211697.
Subcellular location: Cell membrane
Gene Ontology:
Cellular component: plasma membrane
Homologues: Orthologues: mouse Trgv7 (44% identical). Paralogues in human: TRGV3 (92% identical), TRGV2 (77% identical), TRGV4 (75% identical), TRGV8 (74% identical), TRGV1 (73% identical), TRGV11 (25% identical), TRGV10 (24% identical), TRGV9 (23% identical), TRGC1 (0% identical), TRGC2 (0% identical).
Diseases named in the same sentence as TRGV5 in open-access papers:
TRGV5 is named in the same sentence as 2 diseases in open-access papers, as found by Europe PMC text mining. Sharing a sentence is not in itself a finding about the gene and the disease. The quoted sentences say what the papers report.
tumor (2 papers, 2023 to 2024). "The expression of Trgv1, the gene encoding T cell receptor Vγ1 chain, but not Trgv4, Trgv5, Trgv6 or Trgv7 was also upregulated in tumours of Vil Apc Dock2 mice." (PMID 39242821, 2024).
TRGV5 also shares sentences with these, for which no sentence is quoted: prostate tumors (1 paper).